CNPY2 (canopy FGF signaling regulator 2)
Description:
Positive regulator of neurite outgrowth by stabilizing myosin regulatory light chain (MRLC). It prevents MIR-mediated MRLC ubiquitination and its subsequent proteasomal degradation.
Synonyms: MSAP; TMEM4; ZSIG9; HP10390
Tractability: Antibody: UniProt predicts a signal peptide or a membrane-spanning region. PROTAC: ubiquitination databases record sites on it; its protein half-life has been measured.
Gene: Protein-coding gene on chromosome 12 (56,308,024 to 56,316,346, reverse strand). Ensembl gene ENSG00000257727.
Subcellular location: Endoplasmic reticulum
Subcellular location (Human Protein Atlas): Cytosol
Gene Ontology:
Molecular function: protein binding
Biological process: negative regulation of gene expression; regulation of low-density lipoprotein particle clearance
Cellular component: endoplasmic reticulum
Genetic constraint (gnomAD): Loss-of-function variants: 19 observed, 26.84 expected, observed/expected ratio (o/e) 0.71, 90% interval 0.49 to 1.04. The upper end of that interval is the gene's LOEUF score, 1.04, which puts it in group 4 of 6, group 1 being the genes least tolerant of losing a copy. Missense variants: 214 observed, 246.52 expected, observed/expected ratio (o/e) 0.87, 90% interval 0.78 to 0.97. Synonymous variants: 82 observed, 90.41 expected, observed/expected ratio (o/e) 0.91, 90% interval 0.76 to 1.09.
Homologues: Orthologues: chimpanzee CNPY2 (100% identical), rabbit CNPY2 (99% identical), dog CNPY2 (99% identical), pig CNPY2 (99% identical), guinea pig CNPY2 (98% identical), mouse Cnpy2 (97% identical), rat Cnpy2 (91% identical), Caenorhabditis elegans F01F1.15 (34% identical), Drosophila melanogaster sel (26% identical), Caenorhabditis elegans F01F1.11 (21% identical), Caenorhabditis elegans Y47H9C.8 (16% identical). Paralogues in human: CNPY1 (35% identical).
Diseases named in the same sentence as CNPY2 in open-access papers:
CNPY2 is named in the same sentence as 51 diseases in open-access papers, as found by Europe PMC text mining. Sharing a sentence is not in itself a finding about the gene and the disease. The quoted sentences say what the papers report.
colorectal cancer (6 papers, 2017 to 2025). A primary or metastatic malignant neoplasm that affects the colon or rectum. "Another 2017 study involving colorectal cancer patients showed that lower CNPY2 expression (specifically isoform 2) was associated with poorer survival." (PMID 40001982, 2025). "Another 2017 study found elevated CNPY2 expression in colorectal cancer cells compared to normal colonic tissue and epithelium." (PMID 40001982, 2025). "CNPY2’s role in other cancers, including cervical cancer, colorectal cancer, gastric cancer, and esophageal squamous cell carcinoma (ESCC), has also been explored." (PMID 40001982, 2025). "In colorectal cancer, elevated levels of CNPY2 expression were observed in cancerous tissues when compared to healthy controls." (PMID 40001982, 2025). "A 2018 study further evaluated the efficacy of CNPY2 as a biomarker in colorectal cancer, finding that combining CNPY2 with CEA and CA19-9 significantly improved diagnostic accuracy compared to using each marker individually." (PMID 40001982, 2025). "CNPY2 is key regulator of different types of human cancer such as renal cell carcinoma, colorectal cancer, non-small cell lung cancer, and lung adenocarcinoma." (PMID 34715819, 2021). "Sensitivities and specificities of serum CNPY2 isoform 2 concentrations for the diagnosis of different stages of colorectal cancer in patients." (PMID 30070972, 2018). "This is in line with the recent finding that CNPY2 may be a valuable prognostic indicator for several other types of neoplasms including the colorectal cancer, renal cell carcinoma, lung and esophageal squamous cell carcinoma." (PMID 34298825, 2021). "It has been reported that CNPY2 is related to esophageal squamous cell carcinoma (ESCC), colorectal cancer (CRC) and renal cancer." (PMID 29849941, 2018).
glioma (3 papers, 2014 to 2021). A benign or malignant brain and spinal cord tumor that arises from glial cells (astrocytes, oligodendrocytes, ependymal cells). "Our observation of CNPY2 in brain and liver is consistent with previous reports that have demonstrated CNPY2 expression in C6 glioma cells and Huh7 hepatocytes." (PMID 25393402, 2014). "CNPY2 was first revealed as a vital modulator that enhances neurite outgrowth in neuroblastoma and PC12 cells and pro-motes cell migration in rat C6 glioma cells by phospho-rylating and preventing ubiquitination of myosin regula-tory light chain (MRLC)." (PMID 29135454, 2017). "CNPY2 has been shown to participate in outgrowth of neurites by increasing MRLC phosphorylation, which is a key regulatory mechanism in the control of myosin activity and cell motility, and to enhance cell spreading of fibroblasts and migration of rat C6 glioma cells." (PMID 34298825, 2021).
neuroblastoma (3 papers, 2017 to 2024). Neuroblastoma (NB) is the most common solid, extracranial childhood tumor. "This approach reduced the relative level of CNPY2 to about half in the striatal cells, which is in accordance with data obtained with mouse neuroblastoma cells." (PMID 39359687, 2024). "Together these findings demonstrate that CNPY2 overexpression evokes cell protection against ER stress in neuroblastoma cells." (PMID 39359687, 2024). "In these experiments mouse neuroblastoma N2A cells were transfected with CNPY2-dsRed overexpressing construct or by using short hairpin (sh) RNA to reduce CNPY2 levels." (PMID 39359687, 2024). "To substantiate the data, we also studied cell clones of SH-SY5Y neuroblastoma cells stably overexpressing CNPY2." (PMID 39359687, 2024). "Overexpression of CNPY2 enhanced, while downregulation of CNPY2 using shRNA expression, reduced the viability of neuroblastoma cells after tunicamycin." (PMID 39359687, 2024). "Protein canopy homolog 2 (CNPY2) controls the outgrowth of neurites through positive regulation of their outgrowth in neuroblastoma and pheochromocytoma due to stabilizing the myosin regulatory light chain (MRLC)." (PMID 34298825, 2021).
prostate carcinoma (3 papers, 2018 to 2025). A carcinoma that arises from epithelial cells of the prostate gland. "It is conceivable that hypoxia caused by castration may lead to hyper-expression of CNPY2 through the activation of the HRE in the CNPY2 promoter region in prostate cancer cells." (PMID 29707137, 2018). "CNPY2 has also been found to play a role in prostate cancer progression through its modulation of the androgen receptor (AR)." (PMID 40001982, 2025). "In Drosophila models, CNPY2 expression was shown to promote the growth, proliferation, and metastasis of prostate cancer cells." (PMID 40001982, 2025). "In prostate cancer, CNPY2 promotes tumor growth by interacting with MYLIP, preventing the ubiquitination and degradation of androgen receptors (ARs) through the ubiquitin–proteasome pathway." (PMID 40001982, 2025). "This review synthesizes the current understanding of CNPY2’s role in solid tumors, particularly renal cell carcinoma, prostate cancer, hepatocellular carcinoma, and non-small-cell lung cancer." (PMID 40001982, 2025). "The research conducted in prostate cancer (PC) suggested that CNPY2 promoted cell growth of PC cells by inhibition of androgen receptor (AR) protein degradation through MYLIP-mediated AR ubiquitination." (PMID 32039833, 2020). "Using specific antibodies against CNPY2 and AR, immunohistochemistry showed that, as with the cell studies, CNPY2 and AR were co-localized in the prostate cancer tissues of patients." (PMID 29707137, 2018). "We previously identified CNPY2 as a PC cell growth promoter by genetic screening of a prostate cancer model in Drosophila." (PMID 29707137, 2018). "Based on this, it is hypothesized that hypoxia induced by castration may drive the overexpression of CNPY2 observed in castration-resistant prostate cancer." (PMID 40001982, 2025). "This raises the possibility that targeting CNPY2 could be a promising therapeutic approach in castration-resistant prostate cancer, although further research is needed to fully explore this idea." (PMID 40001982, 2025). "Understanding these molecular details is crucial, as targeted disruption of the CNPY2-MYLIP interface could effectively reduce AR levels in prostate cancer cells." (PMID 40001982, 2025). "MYLIP could be a viable therapeutic target in diseases like prostate cancer, where CNPY2 is involved." (PMID 40001982, 2025). "To investigate whether there was a correlation between CNPY2 protein expression and AR protein expression in prostate cancer, we examined CNPY2 and AR in primary prostate cancer tissues." (PMID 29707137, 2018). "Next, we asked whether CNPY2 could regulate the expression level of AR target genes in prostate cancer." (PMID 29707137, 2018). "Furthermore, positive correlation of expression levels between CNPY2 and AR/AR target genes was observed in tissue samples from human prostate cancer patients." (PMID 29707137, 2018). "Based on the CNPY2 and AR expression signature in the different cell lines, we hypothesized that AR expression was regulated by CNPY2 expression in prostate cancer." (PMID 29707137, 2018). "To investigate CNPY2 function, we used human prostate cancer cell lines to model the disease." (PMID 29707137, 2018). "Finally, to investigate whether CNPY2 inhibited MYLIP-mediated AR degradation in prostate cancer cells, AR protein levels were examined by immunoblotting of lysates from either CNPY2 or MYLIP knockdown LNCaP cells." (PMID 29707137, 2018). "The significance of CNPY2 in cancer biology is underscored by its overexpression across various solid tumors, including renal cell carcinoma (RCC), prostate cancer, and hepatocellular carcinoma (HCC)." (PMID 40001982, 2025).
prostate carcinoma (continued). "This potential feedforward mechanism is particularly relevant because it is well known that androgen deprivation through castration can create a hypoxic environment in prostate cancer, leading to increased expression of HIF-1α, which in turn may activate CNPY2 expression." (PMID 40001982, 2025). "Moreover, it remains to be studied whether hypoxia-driven upregulation of CNPY2 (via HIF-1α) additionally modifies any of these post-translational events, creating a feedforward loop that further stabilizes AR in castration-resistant prostate cancer." (PMID 40001982, 2025).
renal cell carcinoma (3 papers, 2021 to 2025).
breast carcinoma (2 papers, 2022 to 2023). "Slc25a24, Cnpy2 and BAX overexpression was reported in breast cancer." (PMID 36151122, 2022).
cervical cancer (2 papers, 2023 to 2025). A primary or metastatic malignant neoplasm involving the cervix. "In cervical cancer cells, CNPY2 upregulation has been linked to a worse prognosis." (PMID 40001982, 2025). "A similar activation of the AKT pathway has also been observed in cervical cancer cells that overexpress CNPY2." (PMID 40001982, 2025). "For example, in cervical cancer cells, CNPY2 upregulation in response to hypoxic stress has been shown to promote cancer cell survival by upregulating glycolysis." (PMID 40001982, 2025).
diabetes (2 papers, 2018 to 2021). "Second, several disease conditions, such as infection, ischemia and diabetes mellitus, which may bias serum CNPY2 isoform 2 levels, could not be taken into consideration." (PMID 30070972, 2018).
gastric cancer (2 papers, 2021 to 2025). A primary or metastatic malignant neoplasm involving the stomach. "In our study, we found that LINC00342 and miR-545-5p regulated cell proliferation, migration, and invasion in gastric cancer by regulating CNPY2." (PMID 34715819, 2021). "Therefore, we suspected that LINC00342 and miR-545-5p may also affect cancer cell apoptosis in gastric cancer by regulating the CNPY2/NF-κB pathway, which will be investigated in our future study." (PMID 34715819, 2021). "In gastric cancer, CNPY2 expression is regulated via the miR-545-5p axis, influenced by the long non-coding RNA LINC00342, which is overexpressed in GC." (PMID 40001982, 2025).
heart failure (2 papers, 2020 to 2021). Inability of the heart to pump blood at an adequate rate to meet tissue metabolic requirements. "CNPY2 attenuated the transition from compensatory hypertrophy to ventricular dilation and heart failure." (PMID 33995012, 2021).
liver cancer (2 papers, 2021 to 2023). An epithelial or non-epithelial malignant neoplasm that arises from the liver. "In Huh7 and HepG2 human liver cancer cells, CNPY2 increase was significantly associated with cell cycle progression, activated cell proliferation and invasion." (PMID 34298825, 2021). "Given the important role in endoplasmic reticulum (ER) stress and proteolysis, we focused on investigation of CNPY2 expression in mouse and human hepatocarcinogenesis and its clinical relevance in virus-associated liver cancer." (PMID 34298825, 2021). "Furthermore, in vitro functional and clinicopathological analyses were carried out to investigate CNPY2 role in human liver cancer and its association with HCV+ HCC patients survival and clinicopathological variables." (PMID 34298825, 2021). "An important role of CNPY2 in cell survival proliferation and invasion potential has been confirmed in experiments with human liver cancer cells." (PMID 37760534, 2023). "CNPY2 potential as a novel molecular target in hepatocarcinogenesis, and as an independent prognostic factor for different types of human liver cancer warrants further exploration." (PMID 34298825, 2021). "To analyze the role of CNPY2 in human liver cancer, we next explored the relationship between CNPY2 expression with clinicopathological variables in HCV+ HCCs by immunohistochemistry." (PMID 34298825, 2021). "Knockdown of CNPY2 in Huh7 and HepG2 human liver cancer cells resulted in significant suppression of cell survival and invasive potential, inhibition of cyclin D1, induction of p21Waf1/Cip1 and suppression of the apoptosis inhibitor Bcl2." (PMID 34298825, 2021). "Canopy homolog 2 (CNPY2) is an interesting protein and angiogenic growth factor which is present in ER lumen, participating in ER stress, and is likely to play a role in NASH-associated liver cancer progression." (PMID 37760534, 2023). "In conclusion, the present results indicate that CNPY2 may become a novel promising molecular and theraupetic target in liver cancer, with involvement in the processes of ER stress, cell survival, proliferation and invasion of tumor cells." (PMID 34298825, 2021).
lung adenocarcinoma (2 papers, 2021 to 2025). A carcinoma that arises from the lung and is characterized by the presence of malignant glandular epithelial cells. "A previously study demonstrated that CNPY2 participated in the regulation of miR-30a-3p in the proliferation, migration and invasion of lung adenocarcinoma cells." (PMID 34715819, 2021).
non-small cell lung carcinoma (2 papers, 2021 to 2025). A group of at least three distinct histological types of lung cancer, including non-small cell squamous cell carcinoma, adenocarcinoma, and large cell carcinoma. "In vitro experiments also revealed that CNPY2 overexpression in non-small-cell lung cancer (NSCLC) cells could reverse cisplatin-induced apoptosis by activating the NF-κB pathway." (PMID 40001982, 2025).
renal carcinoma (2 papers, 2017 to 2018). A carcinoma arising from the epithelium of the renal parenchyma or the renal pelvis.
atherosclerosis (1 paper, 2025). A disease characterized by the build-up of fatty material and calcium deposition in the arterial wall resulting in partial or complete occlusion of the arterial lumen. "CNPY2 aggravated the process of atherosclerosis in ApoE-/- mice in vivo and induced endothelial cell injury in vitro; the latter was markedly attenuated when the cells were treated with the PERK inhibitor GSK2606414." (PMID 41511286, 2025). "Collectively, these findings indicate that the CNPY2 protein functions as an additional component of PERK signaling, suggesting its potential as a novel and promising therapeutic target for vascular disorders, including atherosclerosis." (PMID 41511286, 2025).
Diabetic Nephropathy (1 paper, 2025). "Canopy FGF signaling regulator 2 (CNPY2) which is contributed to ERS is upregulated in the renal tubules of patients with diabetic nephropathy (DN)." (PMID 40211809, 2025).
Huntington disease (1 paper, 2024). Huntington disease (HD) is a rare neurodegenerative disorder of the central nervous system characterized by unwanted choreatic movements, behavioral and psychiatric disturbances and dementia. "In transgenic N171-82Q mice, as a model for Huntington’s disease (HD), the number of CNPY2-immunopositive neurons was increased in the cortex together with CTIP2." (PMID 39359687, 2024).
hypertrophic cardiomyopathy (1 paper, 2019). A condition in which the myocardium is hypertrophied without an obvious cause. "CNPY2 inhibits the transition of hypertrophic cardiomyopathy from compensatory hypertrophy to dilated heart failure." (PMID 31396081, 2019).
keratoconus (1 paper, 2026). A degenerative, structural disorder of the eye, characterized by a cone-shaped protrusion of the cornea. "Moreover, recent meta-analyses have linked CNPY2 downregulation with Keratoconus pathogenesis, further highlighting its tissue- specific roles." (PMID 42016348, 2026).
lung carcinoma (1 paper, 2021). "A previous study found that CNPY2 repressed cisplatin-induced apoptosis in lung cancer by activating the NF-κB pathway." (PMID 34715819, 2021).
memory impairment (1 paper, 2017). "Lap18, Cnpy2, Hnrnpk and Uchl1 expression levels in the rat hippocampus might be related to obesity-induced memory impairments, but the reasons for the dysregulation of these genes were still not clear." (PMID 29937895, 2017).
neuritis (1 paper, 2025). A neuropathy arising from inflammation of one or more nerves. "Inflammatory proteins, such as CNPY2 (neuritis marker) and IL3 (CH3L1), a preinflammatory factor and tumor marker, were also more prevalent, along with immune and wound healing modulators CP4F3 (cytochrome P450) and FKB1A (TGF‐B receptor blocker), which regulate inflammation and immune responses." (PMID 40457720, 2025).
pulmonary fibrosis (1 paper, 2025). Chronic progressive interstitial lung disorder characterized by the replacement of the lung tissue by connective tissue, leading to progressive dyspnea, respiratory failure, or right heart failure. "Together, these data demonstrate that inhaled miR‐30a attenuated bleomycin‐induced pulmonary fibrosis by promoting myofibroblast de‐differentiation through the downregulation of the CNPY2/PERK/DDIT3 signaling pathway." (PMID 40119620, 2025).